TDP1 (tyrosyl-DNA phosphodiesterase 1)
Diseases named in the same sentence as TDP1 in open-access papers (continued):
Sharing a sentence is not in itself a finding about the gene and the disease.
tumor (25 papers, 2015 to 2026). "Tyrosyl-DNA phosphodiesterase 1 (Tdp1) is an important DNA repair enzyme and one of the causes of tumor resistance to topoisomerase 1 inhibitors such as topotecan." (PMID 38279210, 2024). "The involvement of this enzyme in the development of tumor resistance to Top1 inhibitors has been confirmed by studies on Tdp1-deficient human cell lines and mice." (PMID 36615517, 2022). "Thus, the loss of TDP1 function leads to significant accumulation of DNA damage and enhances tumor cell sensitivity to camptothecin derivatives." (PMID 41155491, 2025). "Consequently,TDP1 activity may be a possible cause of tumor resistanceto TOP1 inhibitors used in the clinic." (PMID 41541557, 2025). "TDP1 activity may be a possible cause of tumor resistance to TOP1 inhibitors." (PMID 34768766, 2021). "Tyrosyl-DNA phosphodiesterase 1 (TDP1) is an important DNA repair enzyme and its functioning is considered as one of the possible reasons for tumor resistance to topoisomerase 1 (TOP1) poisons such as topotecan." (PMID 41155491, 2025). "Protein levels and enzymatic activities of TOP1 and TDP1 have been reported to be higher in the tumor tissue of non-small cell lung cancer patients compared to normal tissue." (PMID 41155491, 2025). "It has been shown that these compounds are indeed capable of effectively inhibiting TDP1, as well as sensitizing tumor cell lines to the action of topotecan." (PMID 37298106, 2023). "Overexpression of TDP1 is closely related to tumorigenesis, and is a crucial target for tumor treatment, the TDP1 inhibitor can significantly increase the antitumor effect of drugs." (PMID 37189139, 2023). "These inhibitors are not highly effective against purified Tdp1 and Tdp2 enzymes (ED50 for Tdp1/2 ranges from 1 to 40 μM) but suppress the growth of tumor cells in the nanomolar concentration range." (PMID 37895279, 2023). "And vice versa, overexpression of Tdp1 in tumor cells leads to a decrease in sensitivity to Top1 inhibitors." (PMID 36653585, 2023). "This was unexpected, as TDP1-knockdown human tumor cells that were treated with etoposide, which eventually causes DNA double strand breaks (DSBs), showed increased γH2AX levels." (PMID 36769106, 2023). "TDP1 prevents the action of Tpc, and it is one of the factors of resistance of tumor cells to this drug." (PMID 36982223, 2023). "WB assay results indicated that the protein contents of Top1 and Tdp1 in animal tumor tissues were decreased significantly, especially in the positive control group and the high-concentration PTE treatment group." (PMID 34439157, 2021). "The anti-tumor mechanism of PTE was further explored by detecting the effect of PTE on the DNA repair pathway mediated by Top1/tdp1 in vivo." (PMID 34439157, 2021). "Tdp1 has been reported to repair the CPT-induced DNA damage, thus causing drug resistance in tumor cells." (PMID 34439157, 2021). "Consequently, TDP1 activity may be a possible cause of tumor resistance to TOP1 inhibitors." (PMID 34768766, 2021). "Topoisomerase 1 (Top1) inhibitor is an effective anticancer drug, but several factors limit its clinical application such as drug inactivation, tyrosyl-DNA phosphodiesterase 1 (Tdp1)-mediated tumor drug resistance, and its toxicity." (PMID 34439157, 2021). "PTE has a more stable structure and superior pharmacokinetic properties; thus, it has a better anti-tumor effect in vivo with a higher ability to inhibit Top1 and Tdp1." (PMID 34439157, 2021). "Convincing evidence exists from preclinical studies that the ratio of Tdp1/Top1 activity influences cellular sensitivity to Top1 inhibitors, and that the suppression of Tdp1 activity leads to an increase in the sensitivity of tumor cells to CPTs." (PMID 31878088, 2019). "For six of the genes (CCT5, CD72, COL10A1, FAM177A1, SLC25A12 and TDP1), we were unable to identify a correlation (i.e. concordance) between the copy number alteration and gene expression in six of the tumour samples tested." (PMID 25884485, 2015).
tumor (continued). "On the other hand, tumor cells with overexpression of Tdp1 are less sensitive to these drugs." (PMID 37895279, 2023). "On the other hand, suppression of Tdp1 activity may increase the sensitivity of tumor cells to Top1 inhibitors, potentiating their effects." (PMID 38139858, 2023). "Conversely, increased expression of TDP1 protects tumor cells from these drugs." (PMID 37298106, 2023). "The inhibition of TDP1 sensitizes tumor cells to TOP1 poisons." (PMID 36982223, 2023). "It is well known that Tdp1 is involved in the development of tumor resistance to Top1 inhibitors." (PMID 38139858, 2023). "Treating repair-deficient tumors with TDP1 inhibitors will most likely keep the toxicity and side effects of anticancer treatment at a minimum, since the non-tumor cells in the body will not be repair-deficient and presumably more resistant to drug treatment." (PMID 34300575, 2021). "At the same time, the mRNA expression of Top1 and Tdp1 in tumor tissues was inhibited." (PMID 34439157, 2021). "If a tumor is repair-deficient in other repair processes than the ones involving TDP1, inhibition of TDP1 might be beneficial to achieve synthetic lethality and thereby increase cytotoxicity of tumor cells." (PMID 34300575, 2021). "Indeed, it was found that combined treatment of tumor cells with Tdp1 inhibitors and anticancer drugs camptothecin or topotecan greatly increased the activity of these pharmaceuticals in in vitro and in vivo experiments." (PMID 33808389, 2021). "Thus, Tdp1 is a promising therapeutic target, and its inhibitors are expected to significantly synergize the effects of current anti-tumor therapies, including topoisomerase poisons and other DNA damaging agents." (PMID 33808389, 2021). "Therefore, the inhibition of TDP1 can sensitize tumor cells to the action of TOP1 poisons." (PMID 36982848, 2023). "Previously, we have shown that 7-hydroxycoumarin derivatives with monoterpene moieties 11 and 12 inhibit TDP1 in the submicromolar concentration range and sensitize the action of camptothecin (a Top1 inhibitor of natural origin) and topotecan on the Krebs-2 ascites in vivo tumor model." (PMID 37298106, 2023). "Thus, the aim of our work was to investigate the lipophilic purine nucleosides as the Tdp1 inhibitors and to research whether the leader compounds can sensitize tumor cells in vitro and in vivo to Tpc." (PMID 36615517, 2022). "Therefore, the addition of Tdp1 inhibitors to chemotherapeutic cocktails is a promising strategy for increasing the sensitivity of tumor cells to Top1 inhibitors, in particular Tpc, and reducing their overall toxicity to the body due to a lower therapeutic dose." (PMID 36615517, 2022). "Thus, obtained results and advantageous properties of disaccharide nucleosides suggest that they are novel promising prototypes of medical drugs for further development of tumour sensitisers based on TDP1 inhibition to available antitumour camptothecin-based drugs." (PMID 30191738, 2018). "In this study, based on the hypothesis that TDP1 is a cellular target for 6d, we investigated the sensitizing effect of this compound on the cytotoxic/antiproliferative effect of Tpc on cells with normal and deficient TDP1 level, both in tumor and non-tumor cells." (PMID 41155491, 2025). "In conclusion, in addition to inhibiting the Top1/Tdp1 pathway by PTE and RE, there are other ways to inhibit tumor cells, which need to be further discovered." (PMID 34439157, 2021). "In order to further reveal anti-tumor mechanism of PTE and RE, the effect of PTE and RE on the Top1/Tdp1-mediated DNA repair pathway was further explored." (PMID 34439157, 2021). "The results showed that the GBM patient tumor WCEs exhibited a greater range of TOP1 expression and activity than TDP1." (PMID 31547492, 2019).
neurodegenerative disease (13 papers, 2008 to 2025). A disorder of the central nervous system characterized by gradual and progressive loss of neural tissue and neurologic function. "The clarification of this TDP1-dependent repair pathway has important implications in understanding SSB-associated neurodegenerative disease, transcription-associated genome instability and the efficacy and mutagenic effects of TOP1 poison-based chemotherapy." (PMID 37945566, 2023). "Tdp1, whose failure has been linked to neurodegenerative disease, is a critical participant in repairing DNA damage and is being investigated for its anticancer activity." (PMID 19154573, 2009). "However, we describe here a synergistic decrease in SSBR rates in Aptx−/− cells in which Tdp1, a 3′-end processing enzyme that is mutated in the neurodegenerative disease SCAN1, is also deleted." (PMID 19303373, 2009). "Mutations or loss of function in DNA repair proteins like aprataxin (APTX), tyrosyl-DNA phosphodiesterase 1 (TDP1), or ataxia telangiectasia mutated kinase (ATM) have well-known associations with neurodegenerative diseases." (PMID 39000135, 2024).
neurological disease (6 papers, 2014 to 2025). "Recently it has been clearly documented that deficiencies in DNA end-processing activity (such as that of PNKP, TDP1 and Aprataxin) are linked to neurological diseases." (PMID 25633985, 2015). "Mutations in TDP1 and SPRTN lead to the neurological disorder spinocerebellar ataxia with axonal neuropathy-1 (SCAN1) and Ruijs–Aalfs syndrome (RJALS) characterized by premature ageing and early onset liver cancer, respectively." (PMID 37788708, 2023).
adenocarcinoma (1 paper, 2024). A common cancer characterized by the presence of malignant glandular cells. "Against the adenocarcinoma cells, the conjugation is either detrimental, with an activity lower than that of both parent compounds, when 4 is the anti-TDP1 candidate, or neutral, with regard to the activity of the less active agent, when 5 is the anti-TDP1 candidate." (PMID 39596476, 2024).
blood cancer (1 paper, 2025). "While it remains to be validated whether the increased camptothecin sensitivity of blood cancer cell lines is actually caused by TDP1 deficiencies, these observations suggest opportunities for using TOP1 poisons to better treat certain blood cancers." (PMID 39660638, 2025).
TDP1 also shares sentences with these, for which no sentence is quoted: Ataxia (5 papers); Alzheimer disease (2); cerebellar ataxia (2); Cerebellar atrophy (2); developmental delay (2); microcephaly (2); alcoholism (1); ataxia with oculomotor apraxia type 1 (1); ataxia-oculomotor apraxia-1 (1); breast adenocarcinoma (1); cardiovascular disease (1); cervical cancer (1); Cockayne syndrome (1); Dystonia (1); frontotemporal dementia (1); gastric cancer (1); genetic disease (1); hepatocellular carcinoma (1); Lewis lung carcinoma (1); liver cancer (1); melanoma (1); mitochondrial disease (1); neuropathy (1); oral cavity cancer (1); Parkinson disease (1); peripheral neuropathy (1); Pes cavus (1); pulmonary fibrosis (1); spinocerebellar ataxia type 1 (1); T-cell leukemia (1).
A further 1 disease shares a sentence with TDP1 in 1 paper.